TLR4 (toll like receptor 4)
Diseases named in the same sentence as TLR4 in open-access papers (continued):
Sharing a sentence is not in itself a finding about the gene and the disease.
Chronic colitis (15 papers, 2010 to 2025). A chronic inflammatory disease of the large intestine (colon, cecum and rectum). "As an important mediator involved in the host immune response, TLR4 is overexpressed in inflammation-associated colorectal neoplasia tissues, and contributes to the production of inflammatory factors in chronic colitis." (PMID 31523496, 2019). "MSCs can improve chronic colitis-associated hepatobiliary complications, probably by inhibition of enterogenous endotoxemia and hepatic inflammation through LPS/TLR4 pathway." (PMID 30103680, 2018). "In a DSS-induced murine chronic colitis model, the genetic deletion of TLR4 strongly suppressed colon inflammation and fibrosis." (PMID 33199767, 2020). "We therefore perorally challenged conventionally colonized TLR4-deficient IL10−/− mice and IL10−/− counterparts displaying comparably severe chronic colitis with a clinical MDR PA strain." (PMID 29151895, 2017). "It has been also demonstrated that TLR-4 signaling is crucial for colon carcinogenesis in chronic colitis, being responsible for induction of COX-2, increased prostaglandin E2 production, and activation of EGFR phosphorylation in chronic colitis." (PMID 21059221, 2010). "Differences in mRNA expression of cell polarity subunits were only observed for Scrib and aPkcz after the third cycle of DSS administration in both wildtype and Muc13−/− mice whereas expression of Ceacam 1, and Tlr4 mRNA was found to be significantly altered upon chronic colitis." (PMID 37174625, 2023). "In the present study, TLR4 regulated not only chronic colitis but also fibrosis." (PMID 33199767, 2020). "Therefore, TLR4 signaling pathway may be a potential treatment target for intestinal fibrosis and help patients with chronic colitis prevent or overcome fibrostenosis." (PMID 33199767, 2020). "Oral administration of oligochaetes attenuates acute and chronic colitis in mice by inhibiting the NF‐κB pathway and downregulating its downstream target COX‐2 and upstream target TLR‐4." (PMID 40901656, 2025). "rCT-NAMPT effectively suppressed the severity of disease in DSS-induced acute and chronic colitis models through targeting the colon and inhibiting the interaction of NAMPT with CYBB or TLR4." (PMID 36552583, 2022). "Collectively, in this study, we found that CNQX can suppress the activation of TLR4 signals by targeting MD2 protein, thereby inhibiting inflammation and mucosal barrier damage of chronic colitis." (PMID 34184406, 2021). "To evaluate the role of TLR4 in chronic colon inflammation and fibrosis, we studied a dextran sulfate sodium (DSS)-induced murine chronic colitis model." (PMID 33199767, 2020). "TLR4 triggers elevated production of prostaglandin E2, influences epidermal growth factor receptor signaling (EGFR), and increases TNF-α/NOS2 induction in chronic colitis." (PMID 28408791, 2017). "The gradual recruitment and activation of immune cells to the intestines in chronic colitis, as well as the lack of TLR4 and IL-10 signaling, suggests activation of immune pathways and secretion of cytokines that might differ from acute colitis." (PMID 20976045, 2010).
esophageal squamous cell carcinoma (15 papers, 2014 to 2026). Esophageal squamous cell carcinoma (ESCC) is a type of esophageal carcinoma (EC) that can affect any part of the esophagus, but is usually located in the upper or middle third. "Hsa-circ-0048117 is significantly upregulated and enriched in exosomes secreted by esophageal squamous cell carcinoma after hypoxic preconditioning, and it competes with TLR4 to adsorb mir-140, promoting macrophage polarization towards the M2 phenotype." (PMID 37819576, 2023). "A study in esophageal squamous cell carcinoma showed that inflammation or immune-related TLR4, IL-8, IL-6, and chemokine (C-X-C motif) ligand 2 (CXCL2) were increased upon PLCE1 suppression." (PMID 35054579, 2021). "In Barrett’s metaplasia, the TLR4 protein expression appears upregulated, with the expression intensity correlating with a poor prognosis and with the degree of dysplasia in esophageal squamous cell carcinoma development." (PMID 32424768, 2020). "Though we did not detect TLR4 expression in EC tissue, previous studies showed TLR4 appeared important to the pathogenesis of esophageal squamous cell carcinoma." (PMID 29670922, 2018). "In this study, the relationship between TLR4 and NF-κB p65 protein expressions in tumor tissues after radiotherapy and clinical radiosensitivity of patients with esophageal squamous cell carcinoma was explored." (PMID 25225511, 2014). "Toll-like receptor 4 (TLR4) has been shown to be upregulated in esophageal squamous cell carcinoma." (PMID 27323819, 2016). "TLR-4 is also upregulated in esophageal squamous cell carcinoma (ESCC), and is correlated with poor differentiation and metastasis." (PMID 36838231, 2023).
glomerulonephritis (15 papers, 2009 to 2026). A renal disorder characterized by damage in the glomeruli. "TLR4 in HBV-GN was higher in hepatitis B virus-associated glomerulonephritis." (PMID 36061150, 2022). "Furthermore, TLR4 expression is positively related to tubulointerstitial injury caused by glomerulonephritis." (PMID 36061150, 2022). "A recent study performed on transgenic mice for gp96 (a LPS chaperone that amplifies the TLR4-dependent response) showed that, on this genetic background, the commensal flora spontaneously caused the production of anti-dsDNA antibodies and the development of glomerulonephritis, via TLR4 activation." (PMID 24252506, 2013). "This study investigated the regulatory role and mechanisms of myeloid TLR4 in experimental anti-glomerular basement membrane (GBM) glomerulonephritis (GN)." (PMID 34568976, 2021). "In Faslpr/lpr mutation mice, TLR4 deficiency markedly decreased autoantibody production of anti-dsDNA and anti-ribonucleoprotein (RNP) and improved glomerulonephritis." (PMID 24324506, 2013). "TLR4 as well as the commensal flora has been shown to be essential for the production of anti-dsDNA and the immune complex-mediated glomerulonephritis in transgenic mice expressing surface gp96." (PMID 21860649, 2012). "In this study we have demonstrated that neither TLR2 nor TLR4 deficiency modulates autoantibody production or glomerulonephritis in MRLlpr mice." (PMID 24086313, 2013). "TLR4 is another TLR thought to be involved in the pathogenesis of glomerulonephritis in SLE." (PMID 21860649, 2012). "in which they demonstrated the significance of TLR4+CXCR4+ PCs for autoantibody production and glomerulonephritis development in LN." (PMID 37872565, 2023).
HCMV infection (15 papers, 2007 to 2025). "TLR2 Arg753Gln (rs5743708) and TLR4 Asp299Gly (rs4986790) are correlated with a higher risk of acquiring CMV infection and disease in transplant patients." (PMID 27586547, 2016). "Two candidate genes were screened for association with congenital CMV infection – TLR4 (rs4986790, rs4986791) and TLR9 (rs352140)." (PMID 27586547, 2016). "In the fetuses and newborns with HCMV infection, considering TLR4 896 A>G polymorphic site, the frequency of allele A was 96.7% (29/30), while of G—3.3% (1/30)." (PMID 25844529, 2015). "Taking into consideration TLR4 1196 C>T SNP, we showed the CC genotype at the locus as significantly associated with HCMV infection in fetuses and neonates." (PMID 25844529, 2015). "Additionally, other lesions, located within TLR4 gene, also may have been related to the predisposition to HCMV infections." (PMID 25844529, 2015). "The majority of the children in this study were also involved in earlier studies on the relationship between polymorphisms in the TLR2, TLR4, and TLR9 genes and HCMV infection." (PMID 28046022, 2017). "So far, no other study has shown before any possible involvement of TLR2 2258 G > A, TLR4 896 A > G and TLR4 1196 C > T SNPs in the occurrence of HCMV infection during pregnancy." (PMID 28340580, 2017). "Among various TLR2, TLR4 and TLR9 polymorphisms, TLR2 2258 G>A SNP seems to be an important factor associated with increased risk of congenital HCMV infection in Polish fetuses and neonates." (PMID 28118851, 2017). "Evaluation of the role of single nucleotide polymorphisms (SNPs), located within TLR2, TLR4 and TLR9 genes, in the development of human cytomegalovirus (HCMV) infection in pregnant women and their fetuses and neonates, was performed." (PMID 28340580, 2017). "Polymorphisms of the TLR2 (rs3804100, rs1898830), TLR4 (rs4986791), and TLR9 (rs352140) were shown to have a role in congenital CMV infection." (PMID 27586547, 2016). "Numerous in vitro studies confirmed the role of TLRs in immunity to CMV infection and it was proven that TLR4 and TLR2 recognize CMV." (PMID 27586547, 2016). "Recently, TLR4 and TLR9 polymorphisms were found to play a role in the development of congenital HCMV infection in fetuses and neonates." (PMID 27105145, 2016). "The CC genotype at TLR4 1196 SNP and the GA variant at TLR9 2848 G>A SNP were significantly associated with HCMV infection (P≤0.050)." (PMID 25844529, 2015). "The GC haplotype at TLR4 SNPs and GCA variants at TLR4 and TLR9 SNPs were significantly associated with HCMV infection (P≤0.0001)." (PMID 25844529, 2015). "The stimulation with Poly IC recapitulates the observed pattern triggered by CMV infection with the exception of TLR4 expression." (PMID 25856589, 2015). "The results of our study demonstrate that TLR2 2258 G>A SNP may be an important genetic factor of the previously analyzed TLR2, TLR4 and TLR9 polymorphisms, which is involved in the development of congenital HCMV infection in Polish fetuses and neonates." (PMID 28118851, 2017). "In turn, TLR4 was reported to be correlated with inhibition of HCMV infection." (PMID 28340580, 2017). "In case of TLR4, the molecule was involved in an inhibition of HCMV infection." (PMID 28340580, 2017). "The results showed that TLR2 SNPs rs121917874, rs5743708, and TLR4 SNP rs4986790 are not related to risk of HCMV infection in infants." (PMID 28046022, 2017). "Our recent study in fetuses and neonates, with and without congenital HCMV infection, presented that TLR4 and TLR9 SNPs were associated with the development of congenital cytomegaly." (PMID 28118851, 2017). "Associations between TLR2, TLR4, and TLR9 polymorphisms with HCMV infection have been found." (PMID 28046022, 2017). "Among pregnant women, the low genotypic variability within TLR2 and TLR4 SNPs seems to be the important cause of the lack of any associations with HCMV infection." (PMID 28340580, 2017).
HCMV infection (continued). "In our study, the analyzed TLR4 SNPs were in linkage disequilibrium and, in addition, the GC haplotype, at the described loci, was correlated with HCMV infection and occurred significantly more frequently among symptomatic cytomegaly cases rather than among the asymptomatic ones." (PMID 25844529, 2015). "Additionally, the GCA variants at TLR4 896 A>G, 1196 C>T and TLR9 2848 G>A SNPs were significantly associated with HCMV infection." (PMID 25844529, 2015). "This suggests that TLR ligands may enhance HCMV infection in vivo since GC, T. vaginalis and BV all have TLR ligands (TLR2, TLR4 and TLR2 respectively) associated with their infections." (PMID 18053251, 2007). "Considering TLR4 SNPs, the CC genotype in TLR4 1196 C > T SNP, GC haplotype in both analyzed TLR4 SNPs, as well as GCA multiple variants within the range of TLR4 and TLR9 2848 G > A SNPs, were found to have been correlated with congenital HCMV infection in fetuses and neonates." (PMID 28340580, 2017). "The role of TLR SNPs in congenital and acquired HCMV infection was reported for TLR2, TLR3, TLR4, TLR7, and TLR9 SNPs in various populations." (PMID 34578364, 2021). "Fifty-nine cases of HCMV infection and part of uninfected subjects has been described previously in detail for TLR2, TLR4, and TLR9 SNPs." (PMID 28046022, 2017). "What is more, a significant role in the occurrence of HCMV infection was previously confirmed for TLR2 and TLR4 molecules as well." (PMID 28340580, 2017). "Other studies also showed the SNPs located in TLR2, as well as in TLR3, TLR4, TLR7 and TLR9 genes, to be contributing to HCMV infection." (PMID 28118851, 2017). "So far, no other study has reported similar analyses of the influence of multiple TLR4 and TLR9 SNPs on the congenital HCMV infection, although it seems to be an important trend in the search for the related molecular markers." (PMID 25844529, 2015). "HCMV infection in fibroblasts is also influenced by the TLR3 and TLR4 pathways; stimulation of fibroblasts with TLR3 and TLR4 ligands inhibits viral replication through an IFN-β-dependent mechanism." (PMID 22701276, 2012). "The expression of TLR3 and TLR4 was significantly downregulated during wild-type HCMV infection, but not during infection by mutant HCMV with a deletion of the US7-US16 region." (PMID 31604943, 2019). "The research was aimed to estimate the role of three single nucleotide polymorphisms (SNPs) located in TLR2 gene, and the common contribution of TLR2, and previously studied TLR4 and TLR9 SNPs, to the occurrence of congenital HCMV infection in fetuses and newborns." (PMID 28118851, 2017). "Therefore, the current paper was aimed to describe the role of TLR2, TLR4 and TLR9 SNPs in the occurrence of HCMV infection among pregnant women, acquired within the gestation period." (PMID 28340580, 2017). "It has been reported that TLR9 stimulation plays both positive and negative roles in HCMV infection and that TLR4 and TLR9 activation can increase gene expression from a human CMV enhancer expression plasmid." (PMID 25856589, 2015). "However, other studies showed some role of SNPs in TLR2, TLR3, TLR4, TLR7 and TLR9 genes in HCMV infections." (PMID 25844529, 2015). "Similarly to our study, almost the same frequencies of distinct genotypes in both TLR2 2258 G > A and TLR4 896 G > A SNPs were determined in patients with transplants, with and without clinical signs of HCMV infection." (PMID 28340580, 2017). "cFLIPL-mediated inhibition of caspase-8 and the simultaneous activation of TLR3, but not TNFR1 or TLR4, is required for RIPK3 activation following HCMV infection of monocytes." (PMID 41190811, 2025).
leishmaniasis (15 papers, 2014 to 2024). Infectious disease that is transmitted through the bite of hematophagous female phlebotomine sand flies. "Besides leishmaniasis, TLR4 activation during immunotherapy has been linked to better prognosis against several infectious diseases and cancer models." (PMID 37033485, 2023). "Several reports have shown that the blockade of TLR2 and TLR4 attenuates inflammation in various forms of leishmaniasis." (PMID 37033485, 2023). "TLR4 is reported to be an important receptor for the development of the inflammatory response during leishmaniasis." (PMID 35402314, 2022). "In the murine model of leishmaniasis, TLR4 is required for efficient parasite control and in vitro studies demonstrated that GP29, a L. donovani derived glycoprotein, induced TNF-α and IL-12 production through TLR4 activation." (PMID 34832536, 2021). "The higher production of TNF-α and IL-6 after TLR4a blood stimulation when compared to untreated blood is in agreement with several studies carried out in murine and human leishmaniasis where TLR4 regulated the initial proinflammatory response." (PMID 30539014, 2018). "Of the available adjuvants shown to enhance the T-cell responses that are considered critical for protection against leishmaniasis, TLR4 agonists are by far the most advanced and, indeed, are the only TLR agonists in approved vaccines." (PMID 29263878, 2017). "Murine models of leishmaniasis have linked various TLRs (TLR2, TLR3, TLR4 and TLR9) with enhanced IFN-γ and IL-12 production and parasite control." (PMID 25397678, 2014). "For example, while greater inflammation is seen in leishmaniasis when the host IFN response is induced by parasites harboring Leishmania RNA virus (LRV) others have found TLR4 mediated NFκB activation to be unaffected by IFNγ." (PMID 31293585, 2019). "Early studies concluded that TLR2, TLR4, and TLR9, are involved in the recognition of L. major and that TLR2 ligands play a protective immune role against Leishmaniasis." (PMID 30462645, 2018). "We have shown that combining TLR4 and TLR9 agonists enhanced the efficacy of a therapeutic vaccine against Leishmaniasis." (PMID 24404140, 2014). "Most studies of TLRs in leishmaniasis have been done in the murine models, where expression of TLR2, TLR4, TLR7, TLR8 and TLR9 have been analyzed and related to disease outcome, together with other contributing factors such as Leishmania species and genetic background." (PMID 25397678, 2014).
oral cancer (15 papers, 2019 to 2026). "Polymorphisms in TLR7 and TLR5 were recently associated with oral cancer suppression, while polymorphisms in TLR4 and TLR2 were associated with oral cancer progression." (PMID 38850110, 2024). "Individuals with the combined SNPs of TLR2 and TLR4 had an elevated risk of bacteria-related oral cancer (odds ratio = 1.46; 95% confidence interval: 1.23–1.75)." (PMID 33668218, 2021). "Multiple signalling pathways are involved in the progression of oral cancer, such as Toll-like receptor 4 signalling (TLR4), phosphoinositide 3-kinase (PI3K) pathway, janus kinase (JAK)–signal transduction and activator of transcription (STAT) pathway, etc.." (PMID 38611874, 2024). "Lipopolysaccharide also activates Toll-like receptor 4 (TLR4), which is overexpressed in oral cancers and has been linked to oral carcinogenesis." (PMID 38037123, 2023). "Due to its high levels of expression and its cell surface location, TLR4 is a potential target for a therapeutic approach in oral cancer." (PMID 35327577, 2022). "TLR2 and TLR4 are found in several cell types including oral epithelial cell, gingival fibroblast and with overexpression by oral cancer cells." (PMID 32825570, 2020). "TLR4 expression is upregulated in oral cancer, and elevated TLR4 expression drives the transition of epithelial cells to mesenchymal cells, thereby promoting metastasis, differentiation, and proliferation, and resulting in poor survival and exacerbating disease severity." (PMID 39403369, 2024). "In oral carcinoma, upregulation of TLR4 expression is found and such elevated level of TLR4 drives the transition of epithelial to mesenchymal cells to promote metastasis, cancer differentiation, and proliferation leading to poor survival and increased disease severity." (PMID 37822929, 2023). "Considering that the oral cavity is home to a rich microbiota, and that oral cancer lesions are often colonized by bacteria and fungi, these pathogens, and their product LPS can trigger TLR4, which in turn releases cytokines, producing chronic inflammation and consequently promoting tumor growth." (PMID 35327577, 2022). "Altogether, it appears that the interaction between Fusobacteria and these oral cancer cells is not solely through LPS/TLR4 pathway." (PMID 33391626, 2020).